GNAO1 (G protein subunit alpha o1)
Description:
Guanine nucleotide-binding proteins (G proteins) function as transducers downstream of G protein-coupled receptors (GPCRs) in numerous signaling cascades. The alpha chain contains the guanine nucleotide binding site and alternates between an active, GTP-bound state and an inactive, GDP-bound state. Signaling by an activated GPCR promotes GDP release and GTP binding. The alpha subunit has a low GTPase activity that converts bound GTP to GDP, thereby terminating the signal (By similarity). Both GDP release and GTP hydrolysis are modulated by numerous regulatory proteins (By similarity). Signaling is mediated via effector proteins, such as adenylate cyclase (By similarity). Inhibits adenylate cyclase activity, leading to decreased intracellular cAMP levels (By similarity).
Synonyms: G-ALPHA-o; DEE17; EIEE17; GNAO; HG1G; NEDIM
Tractability: Small molecule: a structure with a bound ligand is known. Antibody: UniProt places it where antibodies can reach, with high confidence; its Gene Ontology location is reachable by antibodies, with high confidence. PROTAC: ubiquitination databases record sites on it; its protein half-life has been measured; a small molecule that binds it is known.
Target class: Other membrane protein
Gene: Protein-coding gene on chromosome 16 (56,189,660 to 56,357,444, forward strand). Ensembl gene ENSG00000087258.
Subcellular location: Cell membrane
Pathways (Reactome):
Signal Transduction: Ca2+ pathway
Gene Ontology:
Molecular function: G protein activity; protein binding; corticotropin-releasing hormone receptor 1 binding; G protein-coupled serotonin receptor binding; G-protein beta/gamma-subunit complex binding; GTPase activity; mu-type opioid receptor binding; GTP binding; guanyl nucleotide binding
Biological process: adenylate cyclase-inhibiting dopamine receptor signaling pathway; adenylate cyclase-inhibiting G protein-coupled receptor signaling pathway; adenylate cyclase-inhibiting serotonin receptor signaling pathway; adenylate cyclase-modulating G protein-coupled receptor signaling pathway; G protein-coupled dopamine receptor signaling pathway; muscle contraction; negative regulation of neurotransmitter secretion; G protein-coupled receptor signaling pathway; negative regulation of insulin secretion; postsynaptic modulation of chemical synaptic transmission; signal transduction
Cellular component: cytoplasmic side of plasma membrane; heterotrimeric G-protein complex; plasma membrane; cell body; dendrite; GABA-ergic synapse; glutamatergic synapse; membrane; parallel fiber to Purkinje cell synapse; postsynaptic membrane; presynaptic membrane
Genetic constraint (gnomAD): Loss-of-function variants: 0 observed, 28.42 expected, observed/expected ratio (o/e) 0, 90% interval 0 to 0.1. The upper end of that interval is the gene's LOEUF score, 0.1, which puts it in group 1 of 6, group 1 being the genes least tolerant of losing a copy. Missense variants: 132 observed, 372.84 expected, observed/expected ratio (o/e) 0.35, 90% interval 0.31 to 0.41. Synonymous variants: 125 observed, 145.11 expected, observed/expected ratio (o/e) 0.86, 90% interval 0.74 to 1.
Gene-disease validity (ClinGen):
ClinGen rates the evidence that GNAO1 causes each of these diseases.
genetic developmental and epileptic encephalopathy (autosomal dominant): Definitive. A complex neurodevelopmental disorder characterized by a range of developmental delays and epileptic encephalopathy phenotypes.
movement disorder (autosomal dominant): Definitive. Neurological conditions resulting in abnormal voluntary or involuntary movement, which may impact the speed, fluency, quality and ease of movement.
Homologues: Orthologues: macaque GNAO1 (100% identical), mouse Gnao1 (98% identical), zebrafish gnao1a (96% identical), zebrafish gnao1b (89% identical), Caenorhabditis elegans goa-1 (82% identical), Drosophila melanogaster Galphao (82% identical). Paralogues in human: GNAI1 (72% identical), GNAI3 (71% identical), GNAI2 (69% identical), GNAT1 (62% identical), GNAT3 (62% identical), GNAT2 (61% identical), GNAZ (60% identical), GNA14 (52% identical), GNA11 (50% identical), GNAQ (50% identical), GNAL (45% identical), GNAS (45% identical), and 3 more.
Diseases named in the same sentence as GNAO1 in open-access papers:
GNAO1 is named in the same sentence as 102 diseases in open-access papers, as found by Europe PMC text mining. Sharing a sentence is not in itself a finding about the gene and the disease. The quoted sentences say what the papers report.
epilepsy (38 papers, 2016 to 2026). A brain disorder characterized by episodes of abnormally increased neuronal discharge resulting in transient episodes of sensory or motor neurological dysfunction, or psychic dysfunction. "Clinically, the N76K variant is associated with severe GNAO1-RD, including developmental delay, epilepsy, and movement disorders." (PMID 41362670, 2026). "This phenotype is highly uncommon, as GNAO1 mutations are typically associated with epilepsy, hyperkinetic movement disorders, and global developmental delay." (PMID 41387899, 2025). "Loss‐of‐function variants in GNAO1 are associated with neurodevelopmental disorders, epilepsy, and movement disorders." (PMID 40542608, 2025). "This presentation is exceptionally rare, as GNAO1 mutations are commonly associated with epilepsy, hyperkinetic movement disorders, and global developmental delay, often accompanied by ID." (PMID 41387899, 2025). "Beyond its use in studying movement disorders, C. elegans offers a unique opportunity to investigate the role of GNAO1 mutations in epilepsy, a common feature of GNAO1 encephalopathy." (PMID 40771566, 2025). "In Homo sapiens, mutations in GNAO1 are linked to neurological disorders, including epilepsy and movement disorders." (PMID 40771566, 2025). "GNAO1-RD patients face a notable risk of mortality during early childhood, often due to refractory epilepsy or dyskinetic crises." (PMID 41153036, 2025). "GNAO1-related disorders encompass a broad phenotypic continuum, including hyperkinetic movement disorders and/or epilepsy, often associated with developmental delay and intellectual disability." (PMID 40826482, 2025). "Several of the MIA increased placental genes were also associated with various CNS disorders, such as epilepsy (Gnao1 and Scn3a)." (PMID 38715090, 2024). "The main GNAO1-associated phenotypes are epilepsy, movement disorder, and global developmental delay." (PMID 40225165, 2023). "Since then, a number of GNAO1 mutations have been linked with different pathological phenotypes, primarily including epilepsy and motor development disorders." (PMID 37887313, 2023). "De novo mutations affecting the G protein α o subunit (Gαo)-encoding gene (GNAO1) cause childhood-onset developmental delay, hyperkinetic movement disorders, and epilepsy." (PMID 36833246, 2023). "In the present study, our data support the findings that patients with GNAO1 variants usually present with MD, epilepsy, and DD at varying degrees." (PMID 37705601, 2023). "In contrast to many other GNAO1 mutations described earlier, this epilepsy- and motor dysfunction-causing protein change demonstrates the preservation of the GTPase activity in the context of an extremely fast GTP uptake." (PMID 37887313, 2023). "The phenotypes of 27 patients (12 male, 15 female) with GNAO1 gene variants included 22 (81%, 22/27) patients with MD, 18 (67%, 18/27) patients with epilepsy, and 13 (48%, 13/27) patients with both MD and epilepsy." (PMID 37705601, 2023). "Dominant de novo mutations in GNAO1 underlie the severe pediatric encephalopathy with motor dysfunction, epilepsy, and developmental delay." (PMID 37887313, 2023). "Loss of function variants in the GNAO1 gene are associated with epilepsy, whereas gain of function variants are reported in patients with movement disorders." (PMID 35725943, 2022). "GNAO1 gene's mutations can cause a complex constellation of neurological disorders including epilepsy, movement disorders, and developmental delay." (PMID 35445545, 2022). "Preclinical studies are needed to understand the pathophysiology of epilepsy in GNAO1 and GNB1 deficiency and to clarify the role of the mTOR signaling pathway activation." (PMID 36003298, 2022).
epilepsy (continued). "Results from published literature and our current study suggested that treatment with topiramate, levetiracetam, or vigabatrin should be recommended for patients with epilepsy and GNAO1 variants." (PMID 34122306, 2021). "In 11 patients with GNAO1 variants, eight (73%, 8/11) had epilepsy, eight (73%, 8/11) had movement disorders, and six (55%, 6/11) had both; all patients had developmental delay." (PMID 34122306, 2021). "GNAO1 gene mutations are associated with a neurodevelopmental disorder characterized by developmental delay, epilepsy, and movement disorder." (PMID 34441836, 2021). "Together with epilepsy or involuntary movements, the phenotypes involved global retardation of motor and intellectual development in patients with GNAO1 variants." (PMID 34122306, 2021). "An avalanche of dominant de novo mutations in GNAO1 have been recently described in paediatric epileptic patients, suffering, in addition to epilepsy, from motor dysfunction and developmental delay." (PMID 33036271, 2020). "A large amount of clinically oriented literature reports on the pathophysiological effects of GNAO1 (the common gene for both Gαo1 and Gαo2) mutations leading to so‐called GNAO1 encephalopathies including symptoms such as epilepsy, movement disorders, developmental delay, or intellectual disability." (PMID 39466989, 2025). "We have earlier shown that among many pathogenic GNAO1 variants, those losing their PM localization invariably lead to clinical manifestations that include epilepsy, while those that clinically lead to the motor dysfunction‐only phenotypes retain their PM localization." (PMID 40337144, 2025). "Similarly, drugs like oxcarbazepine, traditionally used to treat epilepsy, have shown promise in managing movement disorders associated with GNAO1 mutations, further emphasizing the utility of C. elegans in pre-clinical drug screening." (PMID 40771566, 2025). "GNAO1, encoding one of the most abundant Gα proteins in the central nervous system, has been implicated in a spectrum of neurological disorders ranging from epilepsy to movement disorders." (PMID 40870030, 2025). "All children showed pathogenic GNAO1 variants, confirmed with a custom enrichment panel for more than 100 genes related to pediatric MDs or a panel of next-generation sequencing for epilepsy, performed in several neurogenetics laboratories." (PMID 36980817, 2023). "Consequently, GNAO1 is not only in the diagnostic panel for epilepsy but also in the standard gene panel for diagnostic screening of MD in most countries." (PMID 40225165, 2023). "GNAO1 mutations in epilepsy are heterozygous, suggesting their dominant nature." (PMID 33036271, 2020). "In addition, a growing number of genes initially linked to other neurological phenotypes, such as developmental delay, epilepsy, or ataxia, are now recognized to cause prominent dystonia, occasionally in an isolated fashion (e.g., GNAO1, GNB1, SCN8A, RHOBTB2, and COQ8A)." (PMID 36705216, 2022). "GNAO1 encephalopathies manifest in a range of symptoms, including epilepsy, movement disorder, hypotonia, and developmental delay, affecting >400 patients worldwide to date." (PMID 42024408, 2026). "While a notable proportion of individuals exhibit atypical EEG or MRI results, fewer than fifty percent of those with GNAO1 mutations displayed distinctly aberrant EEG patterns, primarily among patients with epilepsy and loss-of-function (LOF) mutations." (PMID 40771566, 2025). "GNAO1 encephalopathy is a rare neurodevelopmental disorder that characterized epilepsy and hyperkinetic movement disorders." (PMID 40826482, 2025).
epilepsy (continued). "GNAO1-related disorders (GNAO1-RD) encompass a wide phenotypic spectrum, including muscular hypotonia, movement disorders (MD), epilepsy, developmental delay, and intellectual disability." (PMID 41153036, 2025). "Molecular functions of GNAO1 are mainly studied in neurons, yet glial cells also express GNAO1 and participate in the pathogenesis of epilepsy." (PMID 41294808, 2025). "Pediatric GNAO1 encephalopathies are characterized by a spectrum of clinical manifestations, including early-onset epilepsy, motor dysfunctions, developmental delay, intellectual disability, and occasional brain atrophy." (PMID 38874642, 2024). "The first mouse model of GNAO1-related epilepsy was created using genetically modified embryonic stem cells with G184S mutation." (PMID 37077890, 2023). "Once these epilepsy and MD models have been validated, they can be implemented to study treatment responses, test new medication, and possibly develop GNAO1-tailored precision medication." (PMID 40225165, 2023). "GNAO1 disorder is a rare autosomal dominant neurodevelopmental syndrome that is clinically manifested by developmental delay, (early onset) epilepsy, and movement disorders." (PMID 40225165, 2023). "Aberrant cAMP synthesis was originally proposed as the main pathogenic mechanism of the disease in GNAO1 disorders, with LOF and GOF alleles that appeared to be primarily associated with epilepsy and MD, respectively." (PMID 36003298, 2022). "Dominant mutations in GNAO1, GNB1, and PDE2A have been associated to a complex early-onset neurological disorder characterized by a variable association of hyperkinetic MD, epilepsy, and developmental delay generally evolving into intellectual disability." (PMID 36003298, 2022). "Our work reveals acylations of several proteins related to epilepsies (GNAO1, SYN1) and a broad spectra of neurodegenerative diseases (TAU and others)." (PMID 36293175, 2022). "GNAO1-related disorders variably combine severe hyperkinetic movement disorders and/or early onset epilepsy." (PMID 34441836, 2021). "GNAO1-related neurological phenotypes were of broad spectrum, including epilepsy, movement disorders, developmental delay, and combinations of all phenotypes." (PMID 34122306, 2021). "Accordingly, we suggest including GNAO1 in diagnostic gene panels for patients with severe speech disorders and ID, even when movement disorders or epilepsy are not present." (PMID 41387899, 2025). "Collects survey-based data on epilepsy-dyskinesia overlap in genetic disorders such as GNAO1." (PMID 40771566, 2025). "Besides DEE, over 30.0% of the GNAO1 patients develop epilepsy at a later stage during childhood with an average onset of 5 years and 3 months." (PMID 40225165, 2023). "On the other extreme of the reported GNAO1 mutations, c.644G > A resulting in the Gαo[C215Y] protein variant has a relatively late age of onset (3 to 12 years), no signs of epilepsy, mild or no intellectual disability." (PMID 35090564, 2022). "G protein subunit alpha O1 (GNAO1)-related disorders (GNAO1-RD) are a group of ultra-rare neurological conditions characterized by a wide spectrum of clinical features, including movement disorders, developmental delay or intellectual disability, epilepsy, and feeding difficulties." (PMID 41362670, 2026). "In a previous study, LOF variants, mostly involving GTPase, led to enhanced cAMP-mediated signaling and calcium channel activity, increasing excitatory neurotransmission and neuron hyperexcitability, which may explain the pathogenesis of GNAO1-related epilepsy." (PMID 37705601, 2023).
epilepsy (continued). "Epilepsy can be prominent in GNB1 and GNAO1 encephalopathy, while it is anecdotical in individuals with HPCA, PDE2A, and PDE10A pathogenic variants." (PMID 36003298, 2022). "Different authors have recently reported that epileptic encephalopathy is, in most cases, related to GNAO1 loss-of-function (LOF) variants, while manifestations of MDs, with or without epilepsy, are predominantly related to gain-of-function (GOF) heterozygous variants." (PMID 36980817, 2023). "While the clinical phenotype associated with ADCY5 and GNAL is characterized by movement disorder in the absence of epilepsy, GNAO1, GNB1, PDE2A, PDE10A, and HPCA have a broader clinical phenotype, encompassing movement disorder, epilepsy, and neurodevelopmental disorders." (PMID 36003298, 2022).